CRP (C-reactive protein)
Diseases named in the same sentence as CRP in open-access papers (continued):
Sharing a sentence is not in itself a finding about the gene and the disease.
infection (continued). "Finding high toxic clozapine concentration, low NCLZ : CLZ ratio and elevated CRP level, even in the absence of recognizable clinical signs of infection, can be used as an indirect indication of infection-induced clozapine toxicity and hence justify the early use of antimicrobial therapy." (PMID 22934219, 2012). "However, neither IL-8 nor CRP had a statistically significant difference when correlating either the presence of infection or the type of infection (P > 0.05)." (PMID 23724320, 2012). "We could not completely exclude the possibility that this CRP level did not reflect chronic inflammation in our uremic patients, although we excluded patients with suspected infection (defined as those with an abnormal WBC count)." (PMID 22583484, 2012). "Most published studies supporting the use of procalcitonin over conventional inflammatory markers (eg C-reactive protein, CRP) have compared procalcitonin in patients with bacterial infection and those with non-infective diseases or other non-bacterial infections." (PMID 23251353, 2012). "Infection, as indicated by elevated acute phase reactants (CRP and AGP), fever (data not shown), or reported recent symptoms (data not shown) was not a significant predictor of DTH to C. albicans; use of alternative biomarker definitions of acute infection did not alter these results." (PMID 22616000, 2012). "Serum blood analysis of CRP as well as haptoglobin yielded no signs of infection or inflammation." (PMID 22718044, 2012). "CRP is less useful in the earliest phases of severe neonatal infection because it is an acute phase reactant and does not peak until 12 to 24 hours after infection and can also be triggered by non-infectious insult such as trauma." (PMID 23198120, 2011). "With no clinical findings suspect for infection a marked drop in CRP-values on the 4-6 postoperative day, further testing may not be necessary." (PMID 21657968, 2011). "As a result, CRP could be a clinically useful bedside biomarker of infection in cancer patients irrespective of the WCC and the degree of immunosuppression." (PMID 21595932, 2011). "Traditionally CRP has been used clinically to monitor infections and immunological disorders, as part of an acute non-specific response to many forms of inflammation, infection, or tissue breakdown." (PMID 28348657, 2011). "• CRP could be a useful biomarker of infection in cancer patients irrespective of the WCC and the degree of immunosuppression." (PMID 21595932, 2011). "Besides IL-6, acute-phase proteins such as C-reactive protein (CRP), and negatives such as albumin and pre-albumin, may be useful as predictors of post-operative infection." (PMID 21668975, 2011). "Serum blood analysis of C-reactive protein (CRP) yielded no signs of infection or inflammation." (PMID 21980467, 2011). "Therefore, the degree of correlation between CRP and LBP may vary, dependent on the individual contribution of extrahepatic sources according to the site of infection." (PMID 21901123, 2011). "The result may also be explained by the fact that those with raised CRP levels had clearcut medical crisis (i.e. infection) rather than multi-factorial functional decline whose discharges were likely to be delayed." (PMID 19161614, 2009). "This fact, also according to Meisner, could in itself explain the elevated CRP measurements observed, regardless of whether infection was present or not." (PMID 20512289, 2009). "Similarly, under either normal or infection-inflammation condition, CRP and MASP-2 did not compete with each other for L-ficolin." (PMID 19180241, 2009). "Neither PCT nor CRP is a useful marker that can identify infection in patients receiving ATG." (PMID 19291300, 2009). "However, the employment of vertebroplasty was brash, given that such a procedure should not be utilized when ESR and CRP are high and infection is suspected." (PMID 19884999, 2009).
infection (continued). "Conspicuous clinical signs like previous septical revision (3 cases), early failure within 5 years (n = 3), and unclear elevated C-reactive protein in connection with persistent hip pain (n = 1) led to septical revision procedure as a precaution not to overlook a creeping infection." (PMID 18644107, 2008). "These clinically applied CRP-assays, however, were only able to detect massive elevations of circulating CRP and were not sensitive enough to accurately measure CRP levels in apparently healthy individuals below the threshold level that suggest an ongoing infection." (PMID 19578488, 2008). "Our study was not designed to find a relationship between CRP and risk of CVD, and we did not exclude other conditions that could explain elevated CRP levels, like intercurrent infections." (PMID 18439295, 2008). "Yet it is not possible to assure these patients were really uninfected, since evidence of no infection was based on negative bacterial cultures, absence of fever, and a normal CRP value, and these criteria may fail in an appreciable number of cases." (PMID 17324267, 2007). "However, PCT concentrations were higher in patients with infection than in those without infection and contributed significantly to the differential diagnosis of elevated CRP concentrations in patients with hemato-oncological conditions." (PMID 18034890, 2007). "Furthermore, we assessed the discrimination between infected and noninfected patients according to the cutoff value for infection diagnosis of CRP (>8.7 mg/dl) and temperature (>38.2°C) published elsewhere." (PMID 16635270, 2006). "Interestingly, several authors found that an infection should be suspected with a steady CRP increase over 2 or 3 days, in the absence of any intervention able to mount an inflammatory response, such as surgery." (PMID 16635270, 2006). "The WBC count and the CRP level are used routinely as markers of infection in daily clinical use, but our findings may suggest that WBC and CRP could probably be markers of active labour without any infection." (PMID 16122384, 2005). "Infection of the lung with either evidence of increased infection parameters (CRP > 2 mg/dl and/or leukocytes> 10 0000/ml) which are not caused by a different pathologic process or evidence of pulmonary infiltration in the chest x-ray, requiring antibiotic therapy." (PMID 15755324, 2005). "PMN count and CRP were not predictive of maternal infection." (PMID 11916180, 2001). "Furthermore, the altered PC/LPC and PE/LPE ratios, which correlated with pro-inflammatory cytokines, CRP levels, and disease severity, suggest that lipid remodeling enzymes such as lysophosphatidylcholine acyltransferase 1/2 (LPCAT1/2) are tightly regulated in infection-induced stress responses." (PMID 41011521, 2025). "It highlights the prognostic and diagnostic value of integrating prothrombotic biomarkers, especially fibrinogen and CRP, into clinical practice, while also suggesting that their elevation may not be limited to infection but extend to exacerbation-related vascular pathology." (PMID 40918901, 2025). "In addition to imaging, laboratory markers such as C-reactive protein (CRP) and white blood cell (WBC) counts provide valuable adjunctive information, with persistently elevated CRP levels serving as a sensitive indicator of ongoing infection and poor treatment response." (PMID 40585707, 2025). "Additionally, the levels of CRP and IL-6, which are more responsive to systemic inflammation and immune activation, were significantly elevated, further supporting the likelihood of an inflammatory response related to RP rather than infection." (PMID 40895557, 2025). "Furthermore, in comparison with CRP or IL-6, presepsin exhibits a faster kinetic response, being detectable within the early hours of infection onset, whereas CRP may remain non-specifically elevated." (PMID 40804836, 2025).
infection (continued). "Third, although infections are a major cause of mortality in patients with extensive burns and can influence immune cell counts, other markers of infection or inflammation, such as CRP and procalcitonin, were not available for all patients and therefore could not be included in the analysis." (PMID 41011096, 2025). "Notably, her general observations remained stable and laboratory findings were non-specific apart from a mildly elevated CRP, which may reflect a reactive inflammatory response rather than overt infection." (PMID 40909052, 2025). "They reported that elevations in CRP and/or ESR were often observed in many inflammatory conditions without infection, and thus were regarded as a false positive marker, although the combination of a normal ESR and CRP level could predict the absence of infection." (PMID 40565991, 2025). "Additionally, since CRP levels in cancer patients can be influenced by inflammatory responses from tumor cells, they may not accurately indicate the presence of an infection." (PMID 38438974, 2024). "Furthermore, the results of our ROC analysis do not identify a specific threshold for WCC and CRP since a limitation is looking at laboratory investigations preoperatively instead of analyzing blood infection markers at a fixed point in time since symptom onset." (PMID 39350859, 2024). "Furthermore, as infected patients often have a poor prognosis, CRP may only be a surrogate for infection rather than a good prognosis marker." (PMID 39575025, 2024). "Additionally, while CRP and white blood cell counts generally indicate infection and inflammation, their patterns may not uniformly align across different diseases." (PMID 39995828, 2024). "This is particularly important in cancer patients because, due to the reduced immunity, IFI may develop with only a few symptoms: refractory fever and increased markers of an ongoing infection (CRP and PCT), which do not respond to broad-spectrum antibiotic therapy." (PMID 39338963, 2024). "The values might not be examined because of infection with elevated CRP values." (PMID 38123748, 2024). "CRP and WBCs may stay elevated longer post-surgery, regardless of infection." (PMID 38279274, 2024). "However, patients with low-virulence PJIs and those without infection had comparable CRP (medians: 12.0 vs. 3.8 mg/L; p = 0.16) and ESR levels (medians: 30.5 vs. 25.0 mm/h; p = 0.15), indicating that these markers are not suitable for the detection of low-virulence PJIs." (PMID 39203582, 2024). "Therefore, maternal peripheral blood levels of inflammatory markers such as CRP and SII should be monitored during the perioperative period to predict outcomes after noninvasive procedures and attention should be paid to monitoring the infection status after cervical cerclage procedure." (PMID 38977997, 2024). "Also, the increased value of CRP in itself does not indicate the existence of infection with the flu virus, nor does the degree of increase in CRP, which might indicate inflammation and clinical presentation intensity, correlating with influenza A infection." (PMID 39064460, 2024). "A progressive decrease in serum CRP content in both groups could indicate the absence of infection." (PMID 37915948, 2023). "The authors concluded that single measurements at ICU admission of PCT and PCR are not helpful (AUC for PCT 0.56 and CRP 0.54) in detecting infections, but baseline values of PCT < 0.3 ng/mL may be considered to rule out community-acquired bacterial co-infections (NPV 91.1%)." (PMID 37887237, 2023). "Recent genetic studies suggest a protective effect of C-reactive protein (CRP) on AN, which may relate to infection susceptibility given that CRP is not simply a marker of inflammation, as is often characterised, and directly participates in processes like phagocytosis." (PMID 36803885, 2023).
infection (continued). "Therefore, the diagnostic value of inflammatory indicators for infection in SLE patients needs to be confirmed by more studies, but in our study, inflammatory indicators such as CRP, PCT, and IL-6 were significantly elevated in the non-surviving group of patients." (PMID 37051301, 2023). "While CRP is not 100% sensitive and low-grade or encapsulated infections may result in less intensive systemic reactions, healthy patients without inflammation, infection, or neoplasm typically exhibit low serum concentrations of CRP." (PMID 37189111, 2023). "On the other hand, Gerven and coworkers stated that in cases of proven spondylodiscitis, the changes in the CRP level are more predictable than the changes in the serial WBC count but their main focus was evaluating the treatment modality rather than diagnosing the infection itself." (PMID 37872533, 2023). "Even after anamnestic and clinical ascertainment that patients do not have any active infection or malignancy, as was the case in this study, CRP concentrations and SLE disease activity may still dissociate and challenge the biomarkers reliability in active SLE." (PMID 38130723, 2023). "Moreover, it was discussed in previous sections that CRP may not predict infections due to less virulent pathogens, and possibly in healthier individuals." (PMID 37873776, 2023). "Notably, traditional PCT or CRP fails to effectively distinguish these different infection types." (PMID 38053180, 2023). "Furthermore, few studies have shown that a single CRP test without consideration of this inflammatory biomarker’s kinetics might convey an erroneous impression of a relatively mild infection." (PMID 35897672, 2022). "However, CRP is a sensitive but non-specific marker of infection and inflammation." (PMID 35335651, 2022). "CRP is a non-specific inflammatory factor and a sensitive acute-phase protein, which could be affected by many factors, such as acute and chronic inflammation, undocumented infection, and trauma." (PMID 35185894, 2022). "Since several LPS species had strong negative correlations with CRP, especially during the early phase, LPS might mainly exert anti‐inflammatory properties during early infection, and the increase in 22:6 LPS during the late phase, especially in severe COVID‐19, might be a compensatory reaction." (PMID 36214754, 2022). "However, PCT may be the only marker to distinguish between infections caused by gram-negative and gram-positive bacteria, as the levels of CRP and D-dimer are not reliable markers to distinguish between these infections." (PMID 36148158, 2022). "However, in our analysis the best predictor of neurological outcome among inflammatory markers and signs was the CRP level on the second day of hospitalization which is unlikely to be influenced by infections because these classically occur later in the course of the disease." (PMID 35618852, 2022). "Therefore, our findings should be interpreted cautiously; mainly, the CRP might reflect the intestinal necrosis that occurs in NEC rather than infection." (PMID 35978027, 2022). "However, CRP is not sensitive to the detection of AL because it may be increased with any other infection." (PMID 33413244, 2021). "CRP levels that do not decline to normal levels during the interim period may indicate that the current treatment protocol has a lower chance of achieving successful infection control." (PMID 34856956, 2021). "However, the thresholds for synovial CRP that we determined were different from previous studies (2.8 mg/l to 9.5 mg/l), which may be due to reduced inflammatory response in chronic PJI patients with low-toxic infections, as well as differences in measurement." (PMID 34372816, 2021).
infection (continued). "Furthermore, there was a significant difference in the CRP levels, possibly indicating that the severity of infection was higher in the blood culture group than in the non-blood culture group, suggesting that clinicians tended to identify pathogens in cases where infection was considered severe." (PMID 33941097, 2021). "We evaluated whether C-reactive protein (CRP) and white blood cell count (WBC) measured fasting 12-24 h after intravenous thrombolysis (IVT) were associated with outcome in AIS patients without concomitant infection." (PMID 33920119, 2021). "Interestingly, when comparing patients who developed a secondary infection early after cessation of dexamethasone (≤ 4 days) to patients who developed such an infection later on (> 4 days), a more pronounced increase in PCT and CRP was apparent in the late infection group." (PMID 34353339, 2021). "CRP, whose serum concentration increases as much as 1000 times (from baseline levels of 0.8-1 mg/L) during acute responses, is the prototypic acute phase protein in humans and clinically used as a sensitive, though non-specific, systemic marker of infection and inflammation." (PMID 34868070, 2021). "Therefore, an increased number of infectious complications may be missed using peak CRP beyond first 48 hours for excluding infections after liver transplantation than after non-transplant abdominal operations." (PMID 32127631, 2020). "However, these may not necessarily be specific for SABSI as, e.g., CRP is an acute inflammatory protein that increases at sites of both infection and inflammation." (PMID 31964768, 2020). "However, the values were not absolute indications of infection because CRP could be influenced by many factors." (PMID 32334610, 2020). "The possibility that CRP could instead constitute a general clinical biomarker of the non-specific acute phase and inflammatory response to injury and infection has been raised, even though the available evidence often does not allow CRP to be considered that way." (PMID 30769887, 2019). "In our case, the infection route could not be definitively identified; however, the patient presented with a 3-day history of sore throat before hospitalisation, and blood test at admission showed a slightly increased serum CRP of 2.8 mg/dL." (PMID 31139474, 2019). "Routine blood markers of infection (leukocyte count, differential count, C-reactive protein (CRP) and procalcitonin (PCT)) may not be elevated early in the course of ventriculitis or are elevated because of drain placement, haemorrhage or concomitant systemic infection." (PMID 31023301, 2019). "Therefore, it is feasible that the reference values of PCT and CRP, those applied to predicting probable infection in most clinical cases, may not be suitable for GPP patients." (PMID 31777354, 2019). "Therefore, PCT has unique advantages in the identification of infectious or noninfectious inflammatory responses and has been reported to be more reliable than traditional indicators such as WBC count, CRP and other markers in distinguishing infection and noninfection." (PMID 30961628, 2019). "Past evidence suggests that there is wide variations in the correlation between ethnicity IL-6 and CRP levels, and given the non-white participants made up only 2% of the total sample, we felt its inclusion would not provide any meaningful comparison across categories of infection." (PMID 29198208, 2018). "Clinical signs of infection (swelling, erythema, fever, positive scintigraphy and macroscopic signs of infection during surgery such as pus) or elevated conventional biomarkers like CRP and leukocytes might be falsely positive or negative." (PMID 29892047, 2018). "Thus, we were interested in whether D-dimer level shows a sharp change at an early postoperative period and it can be used as a promising biomarker for an early diagnosis of the infection by combining the natural progress with commonly used tests such as ESR and CRP." (PMID 29439725, 2018).